TSC1 (TSC complex subunit 1)
Diseases named in the same sentence as TSC1 in open-access papers (continued):
Sharing a sentence is not in itself a finding about the gene and the disease.
tumor (continued). "Our results indicate that unlike what was reported in the brain samples of Tsc2 cKO mice and in tumor cells and sera of patients with TSC2 mutations, the renal polyamine levels and polyamine biosynthesis are not significantly altered in Tsc1 KO vs. Wt mice." (PMID 36142537, 2022). "High vs. low tumor grade had relative over-expression of EIF4EBP1 (log2 fold-change = 0.84, 95% CI 0.46, 1.22) and RPS6KB2 (log2 fold-change = 0.33, 95% CI 0.15, 0.50), but under-expression of TSC1 (log2 fold-change = − 0.23, 95% CI − 0.38, − 0.08)." (PMID 35608730, 2022). "The proportion of individuals with multiple CRs as opposed to an isolated tumour stands at 86% of TSC1 patients and 89% of TSC2 patients with cardiac manifestations." (PMID 35440050, 2022). "Alterations in cell cycle regulatory genes were also detected in the tumor DNA of patients enrolled in the phase Ib BISCAY trial, in which 15% of patients with UC carried an amplification in RICTOR or a deleterious alteration in TSC1/TSC2." (PMID 34030643, 2021). "In addition, well-studied tumor suppressors, such as PTEN (an Akt inhibitor), tuberous sclerosis 1 (TSC1), and TSC2 (mTOR inhibitors), give signals to stimulate autophagy, showing that raised autophagy signaling results in tumor suppression." (PMID 32121322, 2020). "Thus, the tumor suppressors that negatively regulate mTOR (PTEN, AMPK, LKB1, and TSC1/2) will initiate autophagy machinery while, on contrary, oncogenes that activate mTOR (class I PI3K, Ras, and AKT), will inhibit autophagy." (PMID 33297472, 2020). "Further experiments utilizing a FLCN construct harboring the germline mutation of this patient suggest that there may be some ability of FNIP1 and Tsc1 to compensate for one another in the chaperoning of the FLCN and Tsc2 tumor suppressors." (PMID 29774133, 2018). "While the GAP domain of TSC2 contains the tumor suppressor activity, studies indicate that TSC1/TSC2 function primarily as a protein complex, and that TSC1 is required for the stabilization of TSC2 and prevents TSC2 ubiquitination by HERC1 ubiquitin ligase and subsequent degradation." (PMID 27409169, 2016). "Constitutive activation of mTOR signalling by the deletion of the Lkb1/Tsc1/Tsc2 gene in both OSE and stromal cells causes OSE hyperplasia and epithelial OvCa but no stromal tumours." (PMID 27036037, 2016). "Tumour formation has been reported in Lkb1, but not TSC1 or PTEN deletion mice, further suggesting that mTORC1-independent mechanisms contribute to the phenotypes of Lkb1 null mice." (PMID 27039827, 2016). "TSC1 is known to stabilize TSC2 by forming a complex with TSC2 and the genetic data strongly implicate the complex between TSC1 and TSC2 as the functional unit for these tumour suppressors." (PMID 27387347, 2016). "Specifically, tumor suppressor genes that negatively regulate mTOR, such as PTEN, AMPK, LKB1, and TSC1/2 stimulate autophagy while, conversely, oncogenes that activate mTOR, such as class I PI3K, Ras, Rheb, and AKT, inhibit autophagy, suggesting that autophagy is a tumor suppressor mechanism." (PMID 25328887, 2014). "TSC1 and TSC2 form a membrane-bound tumor suppressor complex, in which TSC1 functions as the regulatory component stabilizing TSC2 and facilitating the catalytic activity of TSC2 as a GAP for the small GTPase Rheb, a positive regulator of mTORC1, cell growth and proliferation." (PMID 25360538, 2014). "Besides being directly activated by tumor-suppressor LKB1, AMPK itself regulates the activation of two other tumor suppressors, TSC1 and TSC2, which are critical regulators of Rheb and mTOR." (PMID 22353783, 2012). "At the same time, loss of NF1, TSC1, or TβRII promoted the production of soluble inflammatory mediators such as IL6 and IDO1, which resulted in a non-cell-autonomous immune-suppressive tumor microenvironment that is characterized by increased LAG3+ CD8 and CD4 T cells." (PMID 38997291, 2024).
tumor (continued). "Moreover, TSC1 was significantly downregulated in LMS patient samples, and shRNA-mediated TSC1 knockdown replicated the effects of miR-130b in cell invasion, in vivo tumor growth and metastasis." (PMID 36701370, 2023). "However, no further tumour regression was observed in either TSC1 or TSC2 patients beyond 15.5 years of age, meaning that for approximately 16% of patients, CR persisted into adulthood." (PMID 35440050, 2022). "Our results distinguished FASN, FN, TFRC and TSC1 from previously identified tumour promoters and revealed novel prediction model IPRPs that outperformed the currently established prognostic parameters for anticipating disease course and better clinical management of adult ACC." (PMID 33626208, 2021). "More specifically, it has been highlighted that tumor suppressors that negatively regulate mTOR, (PTEN, AMPK, LKB1, and TSC1/2) initiate autophagy while mTOR activators (such as AKT, class I PI3K, Ras, inhibit autophagy, suggesting that autophagy may have a crucial role in tumor evolution." (PMID 33297472, 2020). "Interestingly, several cancer-related genes (VHL, HIF1A, cMET, phosphatase and tensin homolog, TSC1, BCL2, BRCA1), which include some tumor suppressors, were also found to be overexpressed in both the benign oncocytoma-like region and the high-grade oncocytic carcinoma region." (PMID 25275525, 2014). "By acting on the TSC complex subunit 1 (TSC1)/TSC2 complex and the mechanistic target of rapamycin complex (mTOR) signal transduction, AKT might mediate a variety of cellular functions, including cell proliferation, differentiation, invasion, tumor angiogenesis, and metastasis 65-68." (PMID 36605482, 2023). "We found that the protein expression of NF1, TSC1, and TβRII, but not NF2 and PTEN was downregulated in metastatic nodules compared to the primary tumor tissues." (PMID 38997291, 2024). "FOXA1, STK11, TSC1 and TSC2 were found to have no concordance between tumours and were largely restricted to metastases." (PMID 32811538, 2020). "Here authors show that inactivation of the tumor suppressors NF1, TSC1, and TGF-β RII also promotes a non-cell autonomous change in the tumor microenvironment, characterized by inflammatory features and LAG3+ T cell-mediated immune suppression, which are therapeutically targetable." (PMID 38997291, 2024). "Consequently, massive tumor growth and expansion were detected in the TSC1DC-KO mice but not in the TSC1/mTORDC-DKO mice." (PMID 31433805, 2019).
cancer (125 papers, 2007 to 2025). A tumor composed of atypical neoplastic, often pleomorphic cells that invade other tissues. "This notion is further supported by the reports of increased sensitivity to DNA damage-inducing therapies in cancer patients with mTOR activation caused by germline and/or somatic mutations of TSC1/238–41." (PMID 36396656, 2022). "Activating mutations of proto-oncogenes such as EGFR, PI3K, and AKT as well as inactivating mutations of tumor suppressor PTEN or TSC1/2 causes the activation of the mTOR signaling pathway in a wide range of cancers." (PMID 35805935, 2022). "Onepatient with TSC1 gene mutation in our study had bilateral Wilmstumors, the most common malignant renal tumor in children." (PMID 35638823, 2022). "We proposed that KrasG12D mutation and Tsc1 insufficiency cooperate to drive unique gene expression programs in cancer cells to promote HCC progression and metastasis." (PMID 36451866, 2022). "Accordingly, one study has evaluated mTOR and Hsp90 inhibitors in combination in TSC1 or TSC2 deficient cancer models." (PMID 35883484, 2022). "Here we sought to identify and characterize cancer cell lines with complete loss of either TSC1 or TSC2, and then to examine their sensitivity to a broad panel of kinase inhibitors, with a goal to identify additional inhibitors beyond rapalogs." (PMID 33891611, 2021). "Compared to the overall population, malignant tumors occurred earlier in age and were more common in females and participants with TSC1 mutation." (PMID 34229737, 2021). "In this study we searched for cancer cell lines with bi-allelic inactivating mutations in TSC1 or TSC2 from this resource." (PMID 33891611, 2021). "Downregulation of TSC1 is reported in oral as well as several other cancers and is associated with an unfavourable clinical outcome in patients." (PMID 33833339, 2021). "In conclusion, we have identified and validated five cancer cell lines that have complete loss of either TSC1 or TSC2, and consequent constitutive mTORC1 activation." (PMID 33891611, 2021). "Hereditary kidney cancer patients occupy 5–8% in all the diagnosed ones, and commonly harbor some cancer predisposition genes, such as TSC1/2, CDKN1C and DIS3L2." (PMID 34193180, 2021). "In this study, we identified and validated five cancer cell lines with TSC1 or TSC2 mutations and performed a kinase inhibitor drug screen with 197 compounds." (PMID 33891611, 2021). "In their pan-cancer analyses, the authors reported 2% mutation rate in TSC1 and 4% mutation rate in mTOR." (PMID 35582282, 2019). "Whereas PTEN mutations can lead to malignant cancers, mutations in Tsc1/2 mostly cause benign hamartomas." (PMID 29677182, 2018). "TSC1/2 have been defined as tumor suppressor genes, as they are inactivated/deficient in many cancers, in which mTORC1 kinase is aberrantly activated." (PMID 29491408, 2018). "Increased mTORC1 signaling from TSC1/TSC2 inactivation is found in cancer and causes tuberous sclerosis complex (TSC)." (PMID 28695825, 2017). "Herein, we found that rapamycin treatment promotes TGM2 expression in mTORC1-hyperactive cancer cells, including tsc1-/- and tsc2-/- MEFs, TSC2-deficient patient-derived cells, MCF-7 and 786-O cells." (PMID 26872016, 2016). "The first cancer type in which this was seen was PEComa, a rare sarcoma subtype in which mutations in TSC1 or TSC2 are common." (PMID 26137524, 2015). "Several oncogenes (PI3K, AKT or Ras) and/or tumor suppressors (PTEN, LKB1, or TSC1/2), which are often mutated in cancer, contribute to control mTORC1 activation." (PMID 25051975, 2014). "al. that EVs from Tsc1-deficient cells reduced the activation of mTORC1 and enhanced the expression of miR-212-3p and miR-99a-5p, which have been shown to reduce the growth of a variety of cancers." (PMID 40243914, 2025).
cancer (continued). "The bi-steric mTORC1-selective inhibitor RMC-5552 is now in human clinical trials and, based on the results presented herein, has the potential to benefit patients with TSC syndrome tumors, and patients with the common cancers in which TSC1/TSC2 mutations drive hyperactivated mTORC1 activity." (PMID 37909334, 2023). "The loss of other negative regulators in these signaling pathways and their downstream consequences may be targetable with mTOR kinase inhibitors (e.g., in cancers harboring TSC1/2 and PTEN germline or somatic mutations)." (PMID 35029792, 2021). "Receptor tyrosine kinases (EGFR, HER2, PDGFRa, and FGFR in colorectal, breast, head and neck, gastric cancer, NSCLC, glioblastomas, GISTs, melanoma, etc.), PI3KCA and RAS mutation-mediated PI3K hyperactivity, as well as the loss of PTEN or TSC1/2, leading to mTOR hyperactivity in many cancers." (PMID 35029792, 2021). "More rarely TSC1/TSC2 mutations have been identified in many other cancer types, though whether they are important driver events or passenger mutations is not clear in many instances." (PMID 33891611, 2021). "However, in another sample (MT_006), an inactivating TSC1 mutation went from zero cancer cell fraction in the pre-treatment sample to clonal in the post-treatment sample, in direct contrast to this model." (PMID 30256787, 2018). "Likewise, Pik3cd, involved in the immune response and in cancer is implicated in the mTOR pathway with Ddit4 (also known as Redd1) and Tsc1/2." (PMID 23927422, 2013). "Rheb and TSC1/2 mutations are also frequently observed in cancer." (PMID 22102801, 2011). "Our study thus reveals a role of TSs in regulating metastasis via non-cell-autonomous modulation of the immune compartment and provides proof-of-principle for ICB targeting LAG3 for patients with NF1-, TSC1- or TGF-β RII-inactivated cancers." (PMID 38997291, 2024). "The PI3K/AKT/mTOR pathway is commonly dysregulated in human cancer, due to mutation of dominantly acting oncogenes (PIK3CA, AKT isoforms, MTOR), inactivation of tumor suppressor genes (PTEN, TSC1, TSC2, PIK3R1), and amplification of growth-promoting oncogenes." (PMID 37909334, 2023). "Mutations in the TSC1 and TSC2 genes of these complexes also activate the mTOR pathway and induce cancers." (PMID 37240915, 2023). "Next, we evaluated Gadd45g and Tsc1 expression in human PSCs and cancer cell lines (PANC-1, PACA2, and ASPC1)." (PMID 35211358, 2022). "Conversely, activation of the mTOR pathway confers increased chemosensitivity in cancer cells with genetic ablation of TSC1/2." (PMID 36396656, 2022). "Among these, the genes involved in PI3K-Akt-mTOR signaling axis, such as PTEN, NF1 (neurofibromin 1), TSC1(TSC complex subunit 1), TSC2 (TSC complex subunit 2), were associated with inherited risk for both cancer and ASD." (PMID 36339838, 2022). "AMPK activation leads to inhibition of mTOR phosphorylation at serine 792 and promotes the formation of the TSC1/2 complex, which facilitates apoptosis in cancers." (PMID 36012522, 2022). "For instance, western diet and Tsc1 ablation active aberrant necroptosis in intestinal epithelial cell, then lead to intestinal inflammation and subsequent cancer." (PMID 36065304, 2022). "The reason why some patients with TSC1 or TSC2 mutant cancers have dramatic responses to rapalogs while the vast majority do not, is not understood." (PMID 33891611, 2021). "Most PDAC cancers have RAS mutations leading to activation of the MEK/ERK pathway, which can inactivate TSC1/2 and thereby activate TORC1." (PMID 34638443, 2021). "The mTOR pathway is reported to be aberrantly active in several cancers, including PDAC, in part due to mutations in upstream regulatory molecules including PTEN, AKT, and TSC1/2." (PMID 34638443, 2021).
cancer (continued). "The mTORC1 inhibitor rapamycin and derivative compounds (rapalogues) are used for treatment of various types of cancer, in addition to Tuberous Sclerosis Complex (TSC), an autosomal dominant disorder caused by pathogenic variants in either TSC1 or TSC2." (PMID 33081032, 2020). "The AKT signalling pathway, which promotes cancer cell proliferation, can suppress the TSC1/2 complex, resulting in mTOR1 activation and autophagy inhibition." (PMID 32489327, 2020). "Various cancer types have been shown to carry druggable targets for mTOR inhibitors, including mutations in MTOR, TSC1, TSC2, NF1, PI3KCA, PIK3CG, STK11, and RHEB." (PMID 31443247, 2019). "Relative to the Ngn3-Tsc1−/− sham mice, Ngn3-Tsc1−/− RYGB mice showed a significant increase in levels of TSC1 in both cancer and normal pancreatic tissues." (PMID 30305629, 2018). "Elevated peak nucleotide incorporation rates and yet an over-representation of S-phase cells in cycling TSC1-/- cells intrigued us, since rapid DNA synthesis should intuitively lead to faster progression through S-phase, as typically seen in cancers." (PMID 27863419, 2016). "In both subgroups, there are rare cancer-promoting mutations predicted to activate the PI3K pathway (HRAS, KRAS, PIK3CA, PTEN, and TSC1) and to inactivate the Notch pathway (Notch1 and Notch2)." (PMID 26655088, 2016). "For instance, some germline variants in several well-known loss of function cancer driver genes such as DNM2, SMAD4, NF1, PTCH1, PTEN, SMARCB1, TSC1, cause dominant negative Mendelian diseases." (PMID 27080396, 2016). "Mutations in other cancer‐associated genes such as MAGI3, TSC1, PTPN4, RAB3IP, and RYR1 were also identified." (PMID 26432421, 2015). "First, it is clear that there is a striking correlation between inactivating mutations in TSC1 or TSC2, and activating mutations in MTOR, and response to rapalog therapy in several cancer types." (PMID 26137524, 2015). "Increased activation of mTORC1 is observed in numerous human cancers due to gain-of-function mutations in oncogenes (PI3K, AKT or Ras) and/or loss-of-function mutations in tumor suppressors (PTEN, LKB1, or TSC1/2), upstream regulators of mTORC1." (PMID 25051975, 2014). "Key molecules that modulate autophagy, such as AMPK and TSC1/2, are known to be important in regulating cell survival and proliferation in different kinds of cancer cells." (PMID 25027955, 2014). "We sought to investigate how a CDK4/6 inhibitor modulates the expression of TSC1 in cancer cells." (PMID 38890443, 2024). "However, mutations in the mTOR gene, as well as loss of function mutations in TSC1, TSC2 (tuberous sclerosis proteins 1 and 2), or STK11 (serine/threonine kinase 11), make cancer cells sensitive to mTOR inhibitors." (PMID 39410536, 2024). "Specifically, pathway analysis revealed that miR‐7704, can inhibit targets, including TSC1/2, which is a negative regulator of mTOR1 to promote cell growth, and SFN or stratifin factor, which is associated with cancer treatment resistance and PI3K/AKT signaling." (PMID 38819439, 2024). "In addition, miR-451a has been shown to act as a potential therapeutic agent in cancer treatment by targeting the tuberous sclerosis 1 (TSC1) gene, which activates the PI3K/Akt/mTOR signalling pathway in cancer cells." (PMID 39457889, 2024). "We demonstrated that CDK4/6 inhibitors stabilized TSC1 in cancer cells." (PMID 38890443, 2024). "In addition, according to the results from our 24 pairs of cancer and adjacent-tissue samples, the expression levels of TSC1, MET, and ITGA6 in cancer were significantly higher than those in adjacent normal tissues." (PMID 36261830, 2022).